PREP (prolyl endopeptidase)
Diseases named in the same sentence as PREP in open-access papers (continued):
Sharing a sentence is not in itself a finding about the gene and the disease.
osteoporosis (1 paper, 2025). A condition of reduced bone mass, with decreased cortical thickness and a decrease in the number and size of the trabeculae of cancellous bone (but normal chemical composition), resulting in increased fracture incidence. "This study delves into the role of PREP in osteoporosis, aiming to unravel its underlying mechanisms and therapeutic potential." (PMID 41455745, 2025). "Moreover, our investigation extends to age-related osteoporosis, demonstrating PREP's potential therapeutic efficacy beyond estrogen-deficiency-induced osteoporosis." (PMID 41455745, 2025). "Utilizing murine models and cellular experiments, we systematically investigate how PREP influences osteoblast differentiation and osteoporosis pathogenesis." (PMID 41455745, 2025). "It underscores PREP as a potential therapeutic target for osteoporosis, offering fresh perspectives on its etiology and treatment." (PMID 41455745, 2025). "In summary, this study advances our understanding of PREP's multifaceted role in osteoporosis pathogenesis." (PMID 41455745, 2025). "Prolyl Endopeptidase (PREP), an endopeptidase with diverse roles in neuronal peptide metabolism and various physiological processes, has emerged as a potential player in osteoporosis, though its mechanistic involvement remains largely uncharted." (PMID 41455745, 2025).
primary progressive multiple sclerosis (1 paper, 2015). A multiple sclerosis that is characterized by steady worsening of neurologic functioning, without any distinct relapses or periods of remission. "On the other hand, plasma PREP has been reported particularly reduced in patients with relapsing remitting and primary progressive-multiple sclerosis, pathologies with a prominent inflammatory component." (PMID 26420028, 2015).
pulmonary fibrosis (1 paper, 2023). Chronic progressive interstitial lung disorder characterized by the replacement of the lung tissue by connective tissue, leading to progressive dyspnea, respiratory failure, or right heart failure. "This study demonstrated the involvement of PREP in the pathogenesis of pulmonary fibrosis and that its inhibition by KYP-2047 has a protective role in lung injury, suggesting PREP as a potential target therapy for pulmonary fibrosis." (PMID 37626373, 2023). "Based on this evidence, the aim of this study was to evaluate the beneficial effects of PREP inhibition by KYP-2047 in an in vitro and in vivo model of pulmonary fibrosis." (PMID 37626373, 2023). "Therefore, the aim of this study was to investigate the effect of a selective inhibitor of PREP, known as KYP-2047, in an in vitro and in an in vivo model of pulmonary fibrosis." (PMID 37626373, 2023). "In conclusion, this study demonstrated the involvement of PREP in the pathogenesis of pulmonary fibrosis and that its inhibition by KYP-2047 has a protective role in lung injury induced by BLM, suggesting PREP as a potential target therapy for pulmonary fibrosis." (PMID 37626373, 2023).
renal fibrosis (1 paper, 2015). A final common manifestation of a wide variety of chronic kidney diseases characterized by glomerulosclerosis and tubulointerstitial fibrosis. "Furthermore, it has been shown that PREP is involved in the generation of N-acetyl-seryl-aspartyl-lysyl-proline (Ac-SDKP) form thymosin-β10 in the kidney and that these peptide levels decrease in renal fibrosis and inflammatory cell infiltration in hypertensive rats." (PMID 26420028, 2015).
Sepsis (1 paper, 2020). Sepsis is defined as life-threatening organ dysfunction caused by a dysregulated host response to infection. "Since PREP is also highly expressed in the gastro-intestinal tract and intestinal damage occurs in sepsis, it is possible that PREP could serve as a blood-based biomarker for intestinal damage." (PMID 32315321, 2020). "DPP4, FAP and PREP are good in discriminating between septic shock patients and ICU controls and should be further explored to see whether they are already dysregulated in earlier stages, opening perspectives for their further investigation as biomarkers in sepsis." (PMID 32315321, 2020).
spondylolisthesis (1 paper, 2022). A condition in which there is forward displacement of a vertebral bone over the on below it. "Bioinformatics analysis showed that PREP was upregulated in patients with disc herniation and downregulated in patients with spondylolisthesis, as shown in the heat map." (PMID 35464773, 2022).
ulcerative colitis (1 paper, 2020). An inflammatory bowel disease involving the mucosal surface of the large intestine and rectum. "We found that in the inflamed mucosal specimens of patients with ulcerative colitis, the expression levels of Tβ4 and meprin-α were decreased, while PREP was expressed at similar levels to non-inflamed mucosa." (PMID 32435194, 2020).
cancer (11 papers, 2017 to 2023). A tumor composed of atypical neoplastic, often pleomorphic cells that invade other tissues. "Kallikreins, DPPIV (dipeptidyl peptidase IV), FAP (fibroblast activation protein) and PEP (prolyl endopeptidase) serine proteases are all crucial players in cancer, emerging as clinical markers and prospective diagnostic targets." (PMID 38139365, 2023). "Moving away from trypsin-like serine proteases, DPPIV (Dipeptidyl peptidase IV), FAP (Fibroblast activation protein) and PEP (Prolyl endopeptidase) have emerged as potentially important players in cancer." (PMID 33802262, 2021). "The increased activity of the prolyl endopeptidase FAP enzyme is a hallmark of the tumor stroma, because of the accumulation and activation of cancer associated fibroblasts (CAFs)." (PMID 31881770, 2019). "It was shown that the expression of FAP prolyl endopeptidase, even on the cell surface or solubilized in the plasma, correlates with the malignancy and cisplatin resistance of carcinomas." (PMID 31881770, 2019). "Prolyl endopeptidase FAP reduces scar resolution, activating plasmin inhibitors and blocking fibrinolysis, though questions remain regarding its role in cancer." (PMID 34641541, 2021). "We do not aim to comprehensively review the recent literature on PREP, and fine studies dealing with peripheral actions of PREP and its role in metabolic-inflammatory diseases, including cancer, are not discussed in this paper." (PMID 28261087, 2017).
tumor (11 papers, 2014 to 2025). "PREP, encodes a cytosolic prolyl endopeptidase and has been associated with neoplasms in an number of tissues." (PMID 25148247, 2014). "The relative expression of genes of the RAS and RAS-related enzymes varied considerably in tumor tissue (–4, and S1, S2), with the prorenin receptor having the highest expression followed by prolyl endopeptidase, ACE2, and angiotensinogen." (PMID 34285715, 2021). "The residual activity after DPP4 inhibition could be attributable to other prolyl endopeptidases such as PREP (PREP), which also exhibited high activity in tumor samples, especially in long-term survivors converging with dd-ABPP." (PMID 40425563, 2025). "A high affinity for prolyl endopeptidase (PREP) or DPP, ubiquitously expressed in healthy tissue, would reduce tumor selectivity and result in a lower tumor-to-background ratio." (PMID 39335703, 2024). "The identified gene expression signature included 14 genes, five (CDYL, ATP6V0A4, PREP, RTN41P1, BEND3 and Kif18A) of which were up-regulated in the group of primary tumours of the patients with visceral organ metastasis." (PMID 30961553, 2019). "Other selected targets in clinical trials for CAR T cell therapy, an approach that also requires highly tumor-specific targets, include ERBB2, mucin-16 (MUC16), prominin 1 (PROM1) and the prolyl endopeptidase FAP (FAP)." (PMID 26700623, 2016). "Interestingly, G1/S-specific cyclin-E1, and prolyl endopeptidase FAP were unique in ARMS, denoting its crucial role in cell cycle progression and tumor invasion." (PMID 40710368, 2025). "Conversely, protein levels of these enzymes (e.g. FASN, DPP4, PREP, ELANE) showed only weak or no changes between tumors and nontumor adjacent-tissues, resulting in substantially less accurate tumor classification (right)." (PMID 40425563, 2025).
neurodegenerative disease (7 papers, 2011 to 2023). A disorder of the central nervous system characterized by gradual and progressive loss of neural tissue and neurologic function. "Prolyl endopeptidase (PREP) plays a role in gut metabolic homeostasis and neurodegenerative diseases." (PMID 34095107, 2021).
infection (4 papers, 2020 to 2025). The state of being infected such as from the introduction of a foreign agent such as serum, vaccine, antigenic substance or organism. "Fluorescent probes specific to the prolyl endopeptidase substrate motif were employed and were capable of detecting infection in animals that was comparable to existing diagnostic tests, but varied between A. fumigatus strains." (PMID 33440757, 2021). "Using an animal model, internally quenched fluorogenic probes were utilized to detect proteolytic activity associated with infection, and comparative profiling identified the reproducible activity of prolyl endopeptidase in infected animals." (PMID 33440757, 2021).
neurological disorders (1 paper, 2022). "Furthermore, genetic defects in PreP are linked with human neurological disorders, e.g., cognitive disability/impairment and cerebellar atrophy." (PMID 35383169, 2022).
PREP also shares sentences with these, for which no sentence is quoted: celiac disease (3 papers); bipolar affective disorder (2); schizophrenia (2); acute lung injury (1); acute respiratory distress syndrome (1); Anxiety (1); atherosclerosis (1); autistic spectrum disorders (1); diabetes (1); endothelial dysfunction (1); Enteropathy (1); glioblastoma (1); Huntington disease (1); inflammation (1); intestinal diseases (1); kidney injury (1); liver inflammation (1); metabolic dysfunction-associated steatohepatitis (1); metastatic disease (1); multiple system atrophy (1); muscular dystrophies (1); myocardial ischemia (1); myotonic dystrophy (1); Non-alcoholic Fatty Liver Disease (1); ovarian carcinoma (1); Parkinson's (1); polycystic ovary syndrome (1); Psychosis (1); pulmonary emphysema (1); relapsing-remitting multiple sclerosis (1).
A further 3 diseases each share a sentence with PREP in 1 paper.